CREB1 (cAMP responsive element binding protein 1)
Diseases named in the same sentence as CREB1 in open-access papers (continued):
Sharing a sentence is not in itself a finding about the gene and the disease.
polycystic ovary syndrome (2 papers, 2022 to 2023). A disorder that manifests as multiple cysts on the ovaries. "A study on polycystic ovary syndrome using a mouse model revealed that the enhanced expression of miR-27a-3p significantly inhibits granulosa cell proliferation and promotes apoptosis by targeting Creb1." (PMID 35741771, 2022).
rectal adenocarcinoma (2 papers, 2024 to 2025). "Our study shows that multiple immune genes associated with ASCC3, including JAK1, NFKB1, SEMA5A, NR2C2, CNTF and CREB1, positively impact the prognosis of rectal adenocarcinoma patients." (PMID 40881169, 2025). "ASCC3 is a specific protective factor for rectal adenocarcinoma across various cancer types, particularly in digestive system cancers, and can synergize with several immune-related genes, including JAK1, NFKB1, SEMA5A, NR2C2, CNTF, and CREB1, to influence patient prognosis." (PMID 40881169, 2025).
thyroid (2 papers, 2024 to 2025). "In the comparison between PTC and benign thyroid samples, SFN and CCNA1 were significantly upregulated, whereas FOS, HSPA5, JUN, CREB1, and MAP2K6 exhibited significant downregulation, supporting the findings obtained from the RT-qPCR analysis." (PMID 40722651, 2025). "This fusion reduces the CCDC6-mediated inhibition of CREB1, resulting in increased CREB1 activity and the upregulation of its target genes, such as AREG and cyclin A, thereby promoting thyroid tumorigenesis." (PMID 39457720, 2024).
urinary bladder urothelial carcinoma (2 papers, 2015 to 2016). "In the urinary bladder urothelial carcinoma, CREB1 also plays a tumor suppressor role by transactivating epithelial membrane protein 2 (EMP2)." (PMID 27801665, 2016).
achromatopsia (1 paper, 2024). Achromatopsia (ACHM) is a rare autosomal recessive retinal disorder characterized by color blindness, nystagmus, photophobia, and severely reduced visual acuity due to the absence or impairment of cone function. "Stationary IRDs constituted 14.2% (3.1% albinism, 4.7% CSNB, 5.4% achromatopsia), variants causative for LCA were assigned to 8.5% (CEP290, GUCY2D, RDH12, CREB1, RPE65, RD3), 6% were annotated in RS1, and 3.1% were annotated in CHM." (PMID 39596324, 2024).
Angelman syndrome (1 paper, 2022). A neurogenetic disorder characterized by severe intellectual deficit and distinct facial dysmorphic features. "Similarly, in a genetic mouse model of Angelman Syndrome, the reduced susceptibility to audiogenic-evoked seizures in Ant-134-treated N4 Ube3am–/p+ mice was associated with upregulation of Dcx (mRNA and protein) in the hippocampus and increased Creb1 protein in cortex." (PMID 36240080, 2022).
arenavirus infection (1 paper, 2013). "Thus, comparison of our study with LCMV infection model suggests that arenavirus infection can lead to highly similar transcriptional fingerprints, which have a few notable differences in differing kinetics of interferon induction and expression of CCL5 and CREB1." (PMID 23638192, 2013).
breast disease (1 paper, 2021). "We found that CREB1 is widely expressed in reproductive system or breast disease and urinary system disease." (PMID 33921660, 2021).
cervical disease (1 paper, 2023). "We show that CREB is activated in productively infected primary keratinocytes and that CREB1 expression and phosphorylation is associated with the progression of HPV+ cervical disease." (PMID 37565725, 2023). "Taken together, our results showed that CREB1 expression increased with the progression of cervical disease severity and that CREB1 protein and phosphorylation levels were also increased in HPV+ cell lines and in primary cells containing HPV18." (PMID 37565725, 2023). "Here, we showed CREB1 expression positively correlated with cervical disease progression." (PMID 37565725, 2023).
cervical squamous cell carcinoma (1 paper, 2023). A squamous cell carcinoma arising from the cervical epithelium. "We also explored GSE datasets for CREB1 expression in different CIN grades, representing disease severity, and found that CREB1 expression significantly correlated with increasing CIN grade and was further increased in cervical squamous cell carcinoma." (PMID 37565725, 2023).
coagulation disorder (1 paper, 2022). "Although other pathways regulated by CREB1 could not be excluded, VP35-induced coagulation disorder may play an important role in LPS-mediated mouse mortality." (PMID 35474062, 2022).
colorectal adenocarcinoma (1 paper, 2016). The most common type of colorectal carcinoma. "The data from TCGA database (Colorectal Adenocarcinoma: TCGA, Nature 2012) was analyzed to determine the correlation between CREB1 and RRM2 at mRNA level in clinical CRC specimens by the cBioPortal platform." (PMID 27801665, 2016).
cystic kidneys (1 paper, 2015). "For example, increased transcription of genes regulated by the cAMP responsive element binding protein 1 (CREB1), suggestive of enhanced cAMP signaling, has been reported in cystic kidneys in PKD1 patients." (PMID 26327442, 2015).
ductal breast carcinoma in situ (1 paper, 2019). A carcinoma entirely confined to the mammary ducts. "We analyzed the Oncomine Database and found that the expression of CREB1 in ductal breast carcinoma in situ and invasive ductal breast carcinoma tissues were significantly higher than that in normal breast tissues." (PMID 31754343, 2019).
head and neck cancer (1 paper, 2013). A primary or metastatic malignant neoplasm affecting the head and neck. "Consistent with a positive role in tumor progression, expression of the short LAMA3 isoforms, which is multiply controlled by the transcriptional co-activator EP300, along with the transcription factors AP-1, CREB1 and USF1, is increased and portends a dismal prognosis in head and neck cancers." (PMID 24324612, 2013).
hemorrhage (1 paper, 2022). Loss of blood from the vascular compartment to the exterior or into nonvascular body space as a result of rupture or severance of the blood vessels. "Meanwhile, the transcription of several coagulation-related genes, including THBD and SERPINB2, is substantially upregulated by VP35-dependent CREB1 activation, which may contribute to EBOV-related hemorrhage." (PMID 35474062, 2022).
hepatitis B (1 paper, 2020).
hypertrophic cardiomyopathy (1 paper, 2025). A condition in which the myocardium is hypertrophied without an obvious cause. "In this study, our PPI network results revealed that PPARα, PPARγ, and CREB1 were the potential targets of C. reticulata with higher relevance for combating hypertrophic cardiomyopathy." (PMID 40832599, 2025).
Infertility (1 paper, 2023). "Four transcription regulators (CCND1, FOXO1, CREB1, and HDAC4) were found to be targeted by DE-miRNAs, suggesting that they could be critical regulators in events associated with EMS and may play a role in infertility." (PMID 38002087, 2023).
keloid (1 paper, 2025). An irregularly shaped, elevated mark on the skin caused by deposits of excessive amounts of collagen during wound healing. "This seems contradictory to the conclusion that “hsa_circ_00 26782 inhibits keloids both in vitro and in vivo”, for reason of CREB1 is a transcription factor known to promote cell tumorigenesis and tissue inflammation." (PMID 40823777, 2025). "The findings unveil that the hsa_circ_0026782/CREB1 axis acts as a transcriptional spatiotemporal “molecular break” in the formation of keloids, providing a new target for the therapy of keloids." (PMID 40823777, 2025). "Taken together, suggested that, in vivo, the 1–90 nt region of hsa_circ_00 26782 bound to CREB1 and regulated keloid progression through the hsa_circ_00 26782/CREB1 axis." (PMID 40823777, 2025). "Model for the role of hsa_circ_0026782/p‐CREB1 (Ser142) played in keloid." (PMID 40823777, 2025). "In conclusion, our study presents a novel finding: hsa_circ_00 26782 is downregulated in keloid tissues; it acts as a “molecular break” to inhibit keloid growth by promoting the phosphorylation of CREB1 at Ser142 to enhance CREB1 dimerization, which increases CREB1 DNA‐binding ability." (PMID 40823777, 2025). "To explore whether hsa_circ_00 26782 inhibited keloid growth in vivo by promoting p‐Ser142 of CREB1, we generated CREB1‐Ser142A non‐phosphorylated mutant in hsa_circ_0026782‐overexpression (OE) and CREB1 knockout (CREB1‐KO) hKFs." (PMID 40823777, 2025). "This led to a temporal inhibition of transactivated CREB1 to “switch off” the CREB1‐mediated transcription, and ultimately suppressed the progression of keloids both in vitro and in vivo, which indicates hsa_circ_00 26782 acts as a “molecular break” in keloid progression." (PMID 40823777, 2025). "The results demonstrated that hsa_circ_00 26782 could inhibit keloid progression driven by wildtype CREB1, but could not inhibit keloid progression driven by CREB1‐Ser142A non‐phosphorylated mutant." (PMID 40823777, 2025).
kidney stones (1 paper, 2025). "Notably, elevated CREB1 levels have been linked to pathways involved in diabetic kidney injury, tubular cell damage from kidney stones, and ischemia–reperfusion injuries, highlighting its relevance in the renal pathology and its potential as a therapeutic target." (PMID 41154628, 2025).
measles (1 paper, 2013). A highly contagious viral infection caused by the measles virus. "CREB1 is identified as a component of the measles response (by both TIDAL and DREM)." (PMID 23734902, 2013).
myopia (1 paper, 2023). "Nevertheless, the association between retinal Mapk1 and Creb1, myopia and atropine treatment needs further experimental validation, and future studies are required to explore the exact effects." (PMID 36975502, 2023). "In addition to their associations with estrogen signaling, Mapk1 and Creb1 are involved in several other myopia-related bioactivities in the retina." (PMID 36975502, 2023). "Importantly, among these hub genes, Mapk1 and Creb1 are downstream effectors of atropine treatment, which further confirms that miR-671-5p plays a dominant role in myopia pathogenesis." (PMID 36975502, 2023). "Our results also indicated important roles of Mapk1 and Creb1 in myopia development." (PMID 36975502, 2023). "Although cAMP and dopamine exert potent bidirectional effects on myopic eye growth, it is likely that Creb1 may not act as their downstream effector in myopia development, since it is supposedly upregulated in myopic retinas." (PMID 36975502, 2023).
neuroectodermal tumors (1 paper, 2025). "Molecular studies, specifically fluorescence in situ hybridization (FISH), are essential to confirm the presence of EWSR1::CREB1, which are characteristic of MGNET and further distinguish it from other neuroectodermal tumors." (PMID 40429661, 2025).
parasitic infection (1 paper, 2025). "Cluster MCODE8 included IL6, CREB1, and HMOX1, which were associated with molecular pathway for oxidative stress (WP5477), parasitic infection pathways (R-HSA-9824443), and leishmania infection (R-HSA-9658195)." (PMID 40528239, 2025).
teratoma (1 paper, 2025). A non-seminomatous germ cell tumor characterized by the presence of various tissues which correspond to the different germinal layers (endoderm, mesoderm, and ectoderm). "POU5F1, CREB1, SP1-responsive transcriptome involved in RNA turnover, teratoma formation, and steroid synthesis were found to activated in cluster #4 cancers of the TCGA and GSE99420 cohorts." (PMID 40011822, 2025).
tumor (458 papers, 2009 to 2026). "Most importantly, we developed a tumor-targeted lipid nanoparticle (LNP) system delivering a lactylation-deficient CREB1 K122R competitive peptide." (PMID 42212318, 2026). "Functionally, a lactylation-mimetic CREB1 mutant (K122Q) conferred robust resistance, enhancing cell survival and tumor growth, whereas a lactylation-deficient mutant (K122R) sensitized cells to cisplatin." (PMID 42212318, 2026). "SPIC and MAFB were predominantly expressed in normal and adjacent tissues, while SPP1+ TAM-associated TFs (SREBF1, JUN, SPI1, and CREB1) showed peak expression in tumor core regions." (PMID 40725473, 2025). "To determine the cancer relevance of CREB1 commonly regulated genes, we sought to compare the gene expression change caused by the presence of CREB1 and the gene expression change between tumor and control (ctrl) tissue." (PMID 34641874, 2021). "And, compared with CREB1 and tumor stage, risk score showed higher HR (hazard ratio) in stratifying patients with different prognosis." (PMID 25825983, 2015). "cAMP responsive element binding protein 1 (CREB1) has been reported to be implicated in tumor development and progression of human cancers." (PMID 25825983, 2015). "Overexpression of CREB-1 is associated with excessive proliferation and malignant transformation of ovarian cells demonstrating its protooncogene activity in supporting the initiation, progression, and metastasis of the tumor." (PMID 36497095, 2022). "Interestingly, a recent study revealed the association between CREB1 overexpression with metastasis, tumor stage, and poor outcomes in gastric cancer." (PMID 34947968, 2021). "Importantly, CREB1 also plays a role in cancers, and its expression level is associated with the overall survival and therapy response of tumor patients." (PMID 34641874, 2021). "Sp1 was associated with the third top scoring transcriptional network in tumor tissue after the well-known cancer-related transcription factor c-Myc and also CREB-1 that was recently found to be associated with OVCA cell line platinum sensitivity and overall survival." (PMID 25265318, 2014). "Thus the prognostic model was built as follows: Risk score = 2.011 × CREB1 expression + 2.342 × tumor stage –6.740, where the definition was as follows: for CREB1 expression (0 = low expression and 1 = high expression), and for tumor stage (I = 1, II = 2, III = 3 and IV = 4) in each patient." (PMID 25825983, 2015). "Under conditions of low glucose, the AMPK/CREB1 signaling pathway is activated in tumor cells, resulting in upregulation of SLC2A3 and creating a positive feedback regulatory loop." (PMID 38778609, 2025). "Neoplasms with fusions between Ewing sarcoma breakpoint region 1 (EWSR1) or fused in sarcoma (FUS) genes and genes encoding the CREB family of transcription factors (ATF1, CREB1, and cAMP-responsive element modulator [CREM]) are one such tumor type." (PMID 40242428, 2025). "Among these candidates, CREB1 was identified as a strong candidate due to its biological relevance and potential role in tumour progression." (PMID 40794013, 2025). "Overexpression of miR-101-3p has been shown to suppress cancer cell proliferation, migration, and invasion by directly targeting oncogenic transcription factors such as CREB1, thereby disrupting tumor-promoting signaling pathways." (PMID 40227597, 2025). "According to the previous research reports, activated became phosphorylated CREB1 that played a significant biological function in tumours." (PMID 40794013, 2025). "CREB1 promotes carcinogenesis through a major impact on tumor cell growth, proliferation, survival, metastasis, and invasion." (PMID 40834023, 2025).
tumor (continued). "The results of the tumor‐bearing experiments showed that the tumor volumes of the xenografts decreased in the following order: OE+CREB1‐KO < OE < NC < OE+CREB‐KO+CREB1‐Ser142A." (PMID 40823777, 2025). "CREB1 (cAMP response element binding protein 1) is a member of the basic leucine zipper (bZIP) transcription factors and acts as an oncogene in tumour initiation and progression in various tumours." (PMID 37929660, 2024). "CREB1 promotes cell growth and division, which can contribute to tumor progression in various cancers." (PMID 39456780, 2024). "IHC score indicated that PRR11, KIF11, RACGAP1, YY1, CREB1 expression was significantly increased in HCC tissues compared to adjacent para-tumor tissues." (PMID 39530087, 2024). "CREB1 regulates three important phases in tumor development: cell migration, proliferation, and apoptosis." (PMID 39273390, 2024). "Aberrant activation of cAMP response element-binding protein 1 (CREB1), a crucial transcriptional factor, has been reported to drive tumor progression in various cancers, including OS." (PMID 37285335, 2023). "In the IKE-treated group, CREB1 knockdown reduced the tumor volume and weight, and this effect was reversed by SCD overexpression." (PMID 37957645, 2023). "CREB1 is a DNA-binding protein which stimulates transcription and it is also involved in tumor proliferation and metastasis." (PMID 36769287, 2023). "Multiple studies have demonstrated the role of PKA/CREB1 in tumor biology, the effect of which varies with tumor types and even the same kind of malignancy." (PMID 37957645, 2023). "Molecular research suggests that transcription factors CREB1, AHR, and TOX drive tumor growth and metastasis and are associated with poor prognosis of DLBCL." (PMID 38099311, 2023). "CREB1 oncogene is capable of regulating several microRNAs in various cancers, such as GC, and is involved in tumor growth and cell proliferation." (PMID 37438760, 2023). "As a well-characterized substrate of protein kinase A (PKA) and a transcription factor, the expression and phosphorylation of cAMP-responsive element protein 1 (CREB1) are upregulated in tumor tissue compared to adjacent normal tissue in NSCLC." (PMID 37957645, 2023). "CREB1 expression is negatively regulated by the tumor suppressor microRNA, miR‐203a, and CREB1 phosphorylation is controlled through the MAPK/MSK pathway." (PMID 37565725, 2023). "IHC study showed that the expression of MBNL1 was positively correlated with CREB1 in tumor samples (n = 56, r = 0.419, P = 0.01), and the correlation between CREB1 and MBNL1 was insignificant in normal gastric samples (n = 52, r = 0.153, P = 0.276)." (PMID 35421923, 2022). "Previous studies have shown that CREB1 regulates the expression of some tumor-related genes, such as tumor necrosis factor-α (TNF-α), c-fos, and Bcl-." (PMID 36313570, 2022). "As a proto-oncogene, CREB1 plays a major role in various tumor processes, including proliferation, metastasis, and invasion." (PMID 36313570, 2022). "Thanks to the multi-omics systems biology framework InFlo, it was established that the inhibition of CREB1 phosphorylation sensitizes OC cells to platinum therapy and limits tumor recurrence." (PMID 36497095, 2022). "In the JUB group, p-CREB-1 was noticeably decreased in comparison with that in mice of group B (tumor-bearing control) and group F (tumor-bearing + CUMS), respectively." (PMID 36254198, 2022). "The CTTN levels correlate with increased levels of CREB1 as well as CREB1 downstream signaling toward tumor promotion and cell invasiveness." (PMID 35252867, 2022). "In CRC patients, abnormal overexpression of circ_0136666 and CREB1 was found in CRC tissues and cells, which was associated with tumor size, tumor stage, and metastasis." (PMID 36313570, 2022). "Our results warrant further investigation into the mechanisms by which CREB1 promotes tumor progression and metastasis in OV." (PMID 33921660, 2021).